INS (insulin)
Diseases named in the same sentence as INS in open-access papers (continued):
Sharing a sentence is not in itself a finding about the gene and the disease.
Hypoglycemia (continued). "However, it is known that insulin therapy is related to a high risk of hypoglycemia, which in turn leads to the decline in cognitive function." (PMID 34577866, 2021). "Further studies may also clarify whether the initiation of SGLT-2i may be followed by adjustment in concomitant medications (eg, deprescribing diuretics or insulin), which might be associated with a reduced risk of falls and hypoglycemia events." (PMID 34705014, 2021). "In addition, to cause hypoglycaemia, the normal control that stops insulin secretion from β-cells when blood glucose is low must be defective." (PMID 34170845, 2021). "When initiating a SGLT‐2 inhibitor, consider a lower dose of insulin to reduce hypoglycaemia risk." (PMID 33098260, 2021). "Recent meta-analyses that have compared GLP-1RAs to rapid-acting insulin in patients with maximized basal insulin indicate that, while both treatments are similarly effective, GLP-1RAs are associated with less hypoglycemia and weight loss versus weight gain with rapid-acting insulin." (PMID 34165382, 2021). "Therefore, this study aimed to assess the prevalence and the associated factors of hypoglycemia among T1D patients after insulin use at Metu Karl Referral Hospital in southwest Ethiopia." (PMID 34690922, 2021). "Since SU therapy increases insulin release, there is a risk for hypoglycemia to occur." (PMID 34566892, 2021). "Thus, the risk of hypoglycemia appears to be low with subcutaneous and oral semaglutide by themselves, yet the risk is increased when combined with sulfonylurea and/or insulin therapy." (PMID 34305810, 2021). "The alternative approach of cessation of insulin pumps and switching to a long acting insulin prior to IVGTT may see unpredictable declines in plasma insulin and may risk hypoglycemia while fasting." (PMID 34335462, 2021). "The insulin infusion rate we administered was selected to cause hypoglycemia in humans with average insulin sensitivity, which may vary if the subject is either highly sensitive or resistant to insulin." (PMID 34484102, 2021). "For inpatients with DM, Metreleptin may be administered with insulin or insulin sulfonylurea, but dosage adjustment may be necessary to minimize the risk of hypoglycemia." (PMID 35027962, 2021). "Additionally, treatment of HD is challenging, given the risk of hypoglycemia and the high level of IR accompanied by hyperinsulinemia, leading to variable insulin requirement." (PMID 33445629, 2021). "Also for the different insulin analog products, differences in hypoglycemia risk and glycemic efficacy are minimal despite the substantial cost differences between products." (PMID 33953678, 2021). "However, insulin therapy in these patients must be managed with special care to reduce the risk of exercise-related hypoglycemia." (PMID 33905630, 2021). "People with insulin-treated DM are susceptible to hypoglycemia." (PMID 34497858, 2021). "For Over 30 years, Mühlhauser and co-workers have developed the Düsseldorf model focused on teaching diabetic patients how to match their short acting insulin dose to their carbohydrate load for a better glycemic control, along with a lower risk of severe hypoglycemia." (PMID 34909088, 2021). "In conclusion, the low risk of systemic hypoglycemia and a better CNS absorption has prompted researchers to study the use of intranasal insulin therapy in the treatment of cognitive disorders such as Alzheimer's instead of the commonly used subcutaneous route or an IV route." (PMID 34540446, 2021). "Since exercise is associated with an increased risk of hypoglycemia during the activity, but also causes nocturnal hypoglycemic episodes due to a prolonged elevation of insulin sensitivity, we further studied acute and late-onset hypoglycemia risk for the different treatment adjustment strategies." (PMID 34489869, 2021). "However, decreasing blood glucose values with insulin is associated with a high risk of maternal hypoglycemia, including severe episodes." (PMID 35069449, 2021).
Hypoglycemia (continued). "Nevertheless, the use of liraglutide in combination with insulin or sulfonylureas may increase the hypoglycemia risk." (PMID 34209532, 2021). "Thus, the risk of nocturnal confirmed hypoglycemia was significantly lower in the once-daily IDegAsp group (OR 0.51, 95% CI 0.27 to 0.95, I2 = 66.0) than that in the once-daily basal insulin group." (PMID 34564455, 2021). "After metformin failure, the addition of insulin or sulfonylureas might increase the risk of hypoglycemia and cardiovascular (CV) morbidity." (PMID 33655987, 2021). "Besides weight gain, insulin therapy increases the risk of hypoglycemia, which can be life-threatening." (PMID 33802091, 2021). "Thus, this study showed that TO caused hypoglycaemia and increased the G6P pool for pyruvate production via insulin-dependent mechanism (insulin activation of GCK) in the EATO group and insulin-independent mechanism (via glycogenolysis) in the NHTO group." (PMID 33997754, 2021). "Finally, higher CHFS-B scores were associated significantly with hypoglycemia episode numbers in all category groups (R2=-0.82 for insulin injection; R2=-0.82 for insulin pump; R2=-0.94 for CGM and R2=-0.74 for blood glucose meters; p<0.05)." (PMID 34557162, 2021). "Some tweeters reported issues with their insulin such as insufficient blood glucose reductions, and there were concerns about “Walmart insulin,” with some posts claiming that it is ineffective and caused hypoglycemia." (PMID 33496671, 2021). "Using insulin is often associated with an increased risk of hypoglycemia and weight gain." (PMID 34904015, 2021). "Many factors such as age of the patient, risk of hypoglycaemia, comorbidities, presence of complications, risk of weight gain after insulin initiation, cost of treatment, and so on should be taken into account when tailoring combination therapy to individual patient needs." (PMID 33098260, 2021). "The risk of nocturnal hypoglycaemia following physical activity may be mitigated by reducing basal insulin dose, by including bedtime snacks, and/or by the use of continuous glucose monitoring." (PMID 33098260, 2021). "However, there is a growing number of drugs, such as sodium-glucose cotransporter 2 (SGLT2) inhibitors and long-acting insulin, that are less likely to cause hypoglycemia when used alone, and the primary treatment strategy is to prevent hypoglycemia." (PMID 33750456, 2021). "However, substantial concern remains about the safety of insulin due to the risk of hypoglycaemia using current intermittent blood glucose monitoring." (PMID 33577770, 2021). "Furthermore, the use of one injection every 12 h allows to provide a stable level of insulin all-day, managing to drop also postprandial glycemic values, with an irrelevant risk of hypoglycemia." (PMID 33767671, 2021). "Granting that a relationship exists between EWDR and hypoglycemia, new interventions, such as SU and insulin, could cause EDWR through hypoglycemia owing to their pharmacological mechanisms." (PMID 34337073, 2021). "The purpose of this study was to evaluate the frequency of severe hypoglycemia and its association with common mental disorders in patients with T1D treated with insulin analogues after introduction of these types of insulin in the public health system in Southern Brazil." (PMID 33320451, 2021). "Initially, this involves increasing the basal insulin dose, but there is a need to avoid overbasalization (i.e. titrating to high levels when other options for glycemic control are indicated), which increases the risk of hypoglycemia." (PMID 34165382, 2021). "The other reasons could be possible variation in carbohydrate intake and insulin dosage (for avoiding hypoglycaemia episodes that caused by exercise), stress or stricter medical monitoring, which may all influence glycaemic status." (PMID 33712025, 2021).
Hypoglycemia (continued). "Another contributing factor to increasing HbA1c could be the fear of hypoglycaemia causing some people to intentionally reduce insulin doses and discontinuing treatment." (PMID 34277957, 2021). "Also, incorrect timing or dosing of insulin, stress or exercising more or more vigorously than planned were reported as possible causes of hypoglycaemia." (PMID 34126938, 2021). "Insulin‐induced hypoglycemia is also associated with a neurally driven stimulation of lipolysis." (PMID 33769710, 2021). "Treatment-related complications and reduced oral intake, especially in patients with advanced cancer, could increase the risk of hypoglycemia from insulin and oral hypoglycemic agents; hence, less aggressive measures are warranted in such patients." (PMID 34830886, 2021). "Moreover, we found that the levels of knowledge about hypoglycemia and insulin use were negatively associated with the increased age and education level." (PMID 34497858, 2021). "Using GLP-1RAs instead of insulin cost US$54,851 and US$29,115 per case of all-cause mortality and hospitalized hypoglycemia prevented, respectively, from the payer perspective, and saved US$19,391 and US$10,293, respectively, from the healthcare sector perspective." (PMID 33468131, 2021). "The main question addressed here is whether CHADN predisposes to hypoglycemia when a set amount of insulin was infused." (PMID 33769710, 2021). "In summary, the biochemical tests showed episodes of hypoglycemia with inappropriately high insulin and C-peptide levels, suggesting that the cause may be endogenous insulin secretion." (PMID 34583764, 2021). "Furthermore, an increase in the basal insulin dose will also put the patient at risk of hypoglycemia." (PMID 34071359, 2021). "This is also shown for insulin-producing tumours causing hypoglycaemia." (PMID 34170845, 2021). "In addition, insulin use increases the risk of hypoglycemia, which can stimulate the autonomic nervous system as a counter-regulatory response." (PMID 34496864, 2021). "Also, future studies should collect data on changes to hypoglycemic medications, including alterations to insulin type or dose, as well as substitution of oral treatment with agents that have low risk of hypoglycemia." (PMID 33435992, 2021). "This suggest that performing SMBG could reduce the probability of being prescribed insulin secretagogues, potentially reducing the risk for hypoglycemia." (PMID 33441946, 2021). "HIPOS-WARD reinforces the relevance of these therapies: the occurrence of hypoglycemic episodes was higher in patients on an insulin-based therapy followed by those on a secretagogue-based therapy, which are indeed associated to additional side effects and an increased risk of hypoglycemia." (PMID 33402217, 2021). "The unadjusted incidence of treatment deintensification after a hypoglycemia-associated ED visit or hospitalization was highest among individuals receiving both sulfonylurea and insulin (6677 episodes [48.1%]), followed by those receiving sulfonylurea only (14 192 episodes [44.2%])." (PMID 34726745, 2021). "However, in most cases, it is still difficult to achieve excellent clinical glycaemic control due to the high risks of hypoglycaemia and weight gain caused by inappropriate insulin dosage." (PMID 33746742, 2020). "This extra insulin brings blood sugar level down too low, causing hypoglycemia in the neonates." (PMID 33170888, 2020). "The use of insulin therapy in hyperglycemic preterm infants is itself controversial, since this approach seems to offer little clinical benefit on long-term outcomes while increasing the risk of hypoglycemia." (PMID 33306685, 2020). "However, few studies have reported predictive factors and risk factors for hypoglycemia in hospitalized patients with T2DM treated with intensive insulin therapy." (PMID 33015194, 2020). "Anti-diabetic agents such as insulin and sulfonylureas carry the risk of excessive hypoglycemia." (PMID 32286259, 2020).
Hypoglycemia (continued). "As intensified insulin therapy is linked to a threefold increase in frequency of severe hypoglycemia, implementation of intensive treatment has increased the appearance of fear of hypoglycemia." (PMID 32695233, 2020). "Furthermore, the risk for hypoglycemia, especially at nighttime, is elevated by the potential accumulation of daytime insulin, waning effect of glucocorticoids, and suppressed endogenous cortisol production." (PMID 33348743, 2020). "The susceptibility to hypoglycemia may be linked to the degree of insulin sensitivity of the individual." (PMID 32982972, 2020). "In a randomised treat-to-target trial, IDegAsp BID provided sustained glucose control before, during and after Ramadan fasting in patients with T2D previously treated with basal or premixed insulin ± OADs, with a significantly lower risk of hypoglycaemia than BIAsp 30 BID." (PMID 32290465, 2020). "This approach is straightforward, with the advantage of reducing delayed post-prandial hypoglycaemia, which is particularly concerning in patients taking premixed insulin with the evening meal who may be at risk of nocturnal hypoglycaemia." (PMID 32290465, 2020). "However, the risk of hypoglycemia is low unless coadministered with insulin and insulin secretagogues (e.g., sulfonylureas, glinides)." (PMID 32590982, 2020). "Also, it should be noted that intensive insulin therapy increases the risk of hypoglycemia, which, in turn, worsens CAN." (PMID 32337297, 2020). "However, one study has observed that an adjustment of the baseline insulin dose, decreasing it before exercise, reduces the risk of hypoglycemia during the three hours after performing such exercise." (PMID 32143452, 2020). "Overdose of long-acting insulin can cause unpredictable hypoglycemia for prolonged periods of time." (PMID 33133703, 2020). "Glucose (or dextrose) is given with insulin to minimize the risk of developing hypoglycemia." (PMID 32149451, 2020). "Insulin therapy has always been linked to causing hypoglycemia in the diabetic population." (PMID 32133264, 2020). "In addition to the insulin dose, moderate hypoglycemia was associated with baseline glucose levels and lipid profiles." (PMID 32149152, 2020). "Moreover, the use of multiple doses of insulin therapy or basal-plus insulin therapy was associated with a higher risk of hypoglycemia (P-value 0.012 and 0.028, respectively)." (PMID 32133264, 2020). "Also, female gender, low body weight, and insulin use have been linked in previous studies as the risk factors of severe hypoglycemia." (PMID 32133264, 2020). "Insulin-only AP systems consider only insulin infusion to control BG, and dual-hormone AP systems also consider glucagon infusion to elevate BG to reduce the risk of hypoglycemia." (PMID 32399164, 2020). "Yet, we believe that the strongest independent risk factor for hypoglycemia-related ED and hospital care was the choice of glucose level–lowering medication, with highest risk among patients treated with basal plus bolus insulin regimens, followed by basal insulin and sulfonylurea." (PMID 31922562, 2020). "Interestingly, increased liver steatosis was associated with hypoglycemia and increased plasma insulin concentration." (PMID 32694515, 2020). "Conversely, the inconvenience associated with the insulin therapy, fear of weight gain and the risk of hypoglycemia may adversely affect the patient’s HRQoL." (PMID 31923232, 2020). "Altogether, treatment with empagliflozin may - compared to insulin treatment - reduce risk of hypoglycaemia and work load in relation to glucose measurements and insulin dose changes." (PMID 32539810, 2020). "For example, insulin treatment is associated with a fourfold increased risk of hypoglycemia." (PMID 31915055, 2020). "T2D patients who use other types of antidiabetic medication, especially insulin, might be at risk for developing hypoglycaemia while using this medication in combination with the FMD." (PMID 32580710, 2020).
Hypoglycemia (continued). "Indeed, dexamethasone stimulation test and insulin-induced hypoglycemia confirmed GH deficiency in a superimposable percentage of patients who presented with a pathological GH peak after a first-line dynamic test." (PMID 33362716, 2020). "Owing to the risk of hypoglycemia of intravenous insulin infusion, and the fact that high systemic doses would be needed to achieve functionally effective insulin concentrations in the CNS, this mode of administration is not viable for the psychiatric patients." (PMID 32971941, 2020). "However, several studies have observed an evident association between the use of insulin and higher risk of hypoglycemia." (PMID 32983560, 2020). "Rarely, intentional self-administration of insulin to cause hypoglycemia, i.e., factitious hypoglycemia, can introduce recurrent and serious hypoglycemia and should be diagnosed as having psychological problems including eating disorders or psychiatric disease." (PMID 33042005, 2020). "What is unclear is whether moderate-intensity exercise causes hypoglycemia, and is it related to metabolic health, such as insulin sensitivity." (PMID 32982972, 2020). "On the long term, a reduction in daily insulin dose might lower hypoglycemia risk; however, this should be further validated." (PMID 32351447, 2020). "On the other hand, when the expression level of insulin is too high, the risk of hypoglycemia may also increase." (PMID 33202992, 2020). "However, in the future treatment with CSII, insulin dosage should be reduced even more quickly when blood glucose reaches the target to decrease the potential harms caused by hypoglycemia." (PMID 32149152, 2020). "Further insulin administration may cause severe hypoglycemia, and an intravenous dextrose infusion may be necessary during the test, before finishing." (PMID 32187262, 2020). "Optimising blood glucose control, especially in insulin-treated patients, is challenging because it requires decreasing glycated haemoglobin (HbA1c) to be balanced against potentially increasing the risk of hypoglycaemia." (PMID 32337298, 2020). "The use of insulin could be limited by the risk of hypoglycemia, which is an important adverse effect of insulin therapy." (PMID 32971941, 2020). "We also acknowledge that the compound tends to increase insulin secretion at basal glucose levels, an effect that if mimicked in the in vivo setting could result in increased risk for hypoglycemia." (PMID 32176701, 2020). "Combining metformin with insulin also reduces risk of hypoglycaemia with less weight gain." (PMID 33261058, 2020). "In GDM, short-acting insulin is reported to increase the possibility of hypoglycemia and may cause fluctuations in glycemic control." (PMID 33371325, 2020). "In our opinion, insulin may increase the risk of hypoglycemia in dialysis patients that affected the compliance of combined OHA." (PMID 33172034, 2020). "It is well known that insulin and SU are the most common causes of hypoglycemia." (PMID 32774458, 2020). "Clinicians caring for patients at risk for hypoglycemia may want to preferentially prescribe medications other than insulin and sulfonylurea whenever possible." (PMID 31922562, 2020). "In addition, below-target individuals were more frequently males and less frequently on insulin and agents causing hypoglycaemia and showed a better CVD risk profile than above-target patients." (PMID 31963486, 2020). "Consequently, clinical decisions on glycemic control are often made according to the relative benefits of insulin therapy versus the risk of hypoglycemia." (PMID 32256577, 2020). "SGLT2 inhibitors are associated with minimal risk of hypoglycemia, particularly severe hypoglycemia, as a result of its insulin-independent mechanism of action, enabling it to be used as monotherapy or as a component of combination therapy with other antihyperglycemic agents." (PMID 33041801, 2020).